ANXA1 (annexin A1)
Diseases named in the same sentence as ANXA1 in open-access papers (continued):
Sharing a sentence is not in itself a finding about the gene and the disease.
tumor (continued). "The process of immune response to tumor cell was not much different between tumors in annexin A1 ko and wild-type conditions, consistent with our notion that it was the tumor stroma that made the tumor development significantly different in annexin A1 negative condition." (PMID 23077482, 2012). "Elevated ANXA1 levels in the immune cells of PD‐1 nonresponders may also contribute to the polarization of macrophages towards an M2 phenotype, which is well‐known for its tumor‐promoting and immunosuppressive activities." (PMID 40744683, 2025). "Notably, TRIM31 (logFC = 1.14), ANXA1 (logFC = 1.05), GBP1 (logFC = 1.01), BIRC3 (logFC = 0.99), APOL1 (logFC = 0.97), IL18 (logFC = 0.94), ANXA2 (logFC = 0.89), BHLHE40 (logFC = 0.83), and EPHA2 (logFC = 0.75) exhibited significant upregulation in tumour tissues." (PMID 38254861, 2024). "Furthermore, the potential of AnxA1 serum levels as a tumor biomarker has not been well explored." (PMID 36766767, 2023). "In addition to regulating membrane trafficking, proliferation, differentiation, and apoptosis, AnxA1 inhibits Phospholipase A2 (PLA2) in the cytoplasm and impedes the release of arachidonic acid, which is a key contributor to the development of the tumor microenvironment (TME)." (PMID 35626741, 2022). "Additionally, exosomal EGFR, ANXA1 and programmed cell death (PD)-1/PD-ligand 1 (PD-L1) pathway (tumor suppressor in HNSCC) have been identified as potential biomarkers for predicting prognosis and therapeutic monitoring in tumor derived exosomes of HNSCC patients." (PMID 35387114, 2022). "In both the human lung tumor and the mouse models we tested, there was no apparent correlation between anxA1 expression levels in the tumor vasculature and the tumor parenchyma, suggesting that the function of anxA1 in these cell types may be independent of each other." (PMID 32497150, 2020). "In addition to this, we analyzed whether the associations of ANXA1 and CALD1 with TTP were independent of each other in the subset of 235 tumor tissues for which both measurements were available." (PMID 26657294, 2016). "Thus, we cannot rule out the possibility of ANXA1 as a tumor suppressor even if ANXA1 staining could not be observed in normal gastric mucosa in those studies." (PMID 25038797, 2014). "Before injecting the cells into mice, we conducted proliferation and self-renewal assays in vitro to ensure that ANXA1-KO, HOPX-KO, and RFX4-KO cells exhibited no discernible advantages in growth or tumor-forming capabilities." (PMID 40683881, 2025). "Meanwhile, compared with PTC patients with smaller tumor size (no more than two centimeters), PTC patients in T2 and T3 status showed higher ANXA1 protein levels." (PMID 33531975, 2021). "Only nine patients presented recurrent tumours within this time period, and neither ARID1A nor ANXA1 expression predicted trastuzumab resistance in this group of BrC patients." (PMID 33276477, 2020). "The tumour mass in mice implanted with ANXA1 KO MIA PaCa-2 did not appear significantly smaller if compared with those extracted from control mice, as confirmed by both the evaluation of tumour weight and the macroscopic observation." (PMID 27412958, 2016). "Moreover, the possible mechanism of action of 5-AZA, whether dependent on ANXA1 or not, and, on the other hand, all the potential activities of this protein (i.e., tumor progression, tumor microenvironment and interaction between tumor and other cell populations) need to be further addressed." (PMID 40227604, 2025). "However, once cleaved by proteases, AnxA1 is no longer able to inhibit PLA2 and in this way, it promotes tumor progression." (PMID 34208346, 2021). "Although induction of anxA1 expression in lung tumor vasculature was not as prevalent and widespread as that seen in other tumor vascular targets, notably B7-H3 and PSMA, these data validate anxA1 as a potential tumor vascular drug target in a proportion of human lung tumors." (PMID 32497150, 2020).
cancer (298 papers, 2007 to 2026). A tumor composed of atypical neoplastic, often pleomorphic cells that invade other tissues. "Our results show that the Arg/N-degron pathway modulates exosome-mediated apoptosis in cancer cells under oxidative stress underlying RILP-dependent secretion of ANXA1." (PMID 40520087, 2025). "Loss of ANXA1 causes uncontrolled transformation of normal fibroblasts into cancer-associated fibroblasts, with TGF-β secreted by malignant epithelial cells accelerating this transformation process." (PMID 40115255, 2025). "It is likely that the effects of ANXA1 expression are different even in different subtypes of the same cancer, through ANXA1 gene mutations, epigenetic changes, and post-translational modifications to the ANXA1 protein." (PMID 40361334, 2025). "Altered expression levels of ANXA1, including both increases and decreases, have been linked to cancer progression and clinical outcomes." (PMID 40361334, 2025). "Aberrant hypermethylation of ANXA1 is associated with its aberrant expression and a variety of cancers." (PMID 40551992, 2025). "To date, few studies have addressed the underlying mechanisms responsible for the loss of ANXA1 expression in this type of cancer." (PMID 40227604, 2025). "ICD is associated with the release of various damage-associated molecular patterns (DAMPs) from dying cancer cells, including calreticulin, ATP, annexin A1, type 1 interferon, and high-mobility group box." (PMID 39726713, 2024). "More recently, the ANXA1 expression in cancer was associated with the disease progression by mediating signaling pathways." (PMID 39194522, 2024). "ANXA1, annexin A1, plays an important role in immunity and inflammation and is associated with various diseases and cancers." (PMID 37091170, 2023). "Many types of cancer cells also express AnxA1, and its effects are associated with cancer development by inducing proliferation, angiogenesis, stemness, and cell invasion in FPR-dependent pathways." (PMID 36766767, 2023). "Annexin-A1 (ANXA1), a glucocorticoid-regulated protein with immune-regulatory properties, has been implicated in the growth and metastasis of many cancers." (PMID 35382852, 2022). "ANXA1 is implicated in multiple functions essential in cancer, including cell proliferation, apoptosis, chemosensitivity, metastasis, and invasion." (PMID 35664067, 2022). "Annexin A1 (ANXA1), a Ca2+-regulated phospholipid-binding protein, has been demonstrated to be implicated in the progression and prognosis of many cancers." (PMID 34991599, 2022). "Similar observations have been reported in colorectal cancer, where ANXA1 expression was associated with resistance to treatment with 5‐fluorouracil, a key drug used in the treatment of this cancer." (PMID 35146757, 2022). "Upregulation of several of these genes, for instance, PTPRZ1, WNT5A, S100A4, or ANXA1/2, has been linked to cancer invasion and aggressiveness in some solid tumors, including GBM25–30." (PMID 34112916, 2021). "Since ANXA1 expression was linked to EMT in multiple cancer types, we first investigated the relationship between ANXA1 expression and EMT in PC." (PMID 33804148, 2021). "Annexin A1 faulty expression has been associated with cancer disease, but its actual role is unclear." (PMID 34444893, 2021). "Functional analyses suggest that ANXA1 correlates with the immune-related function and cancer hallmark." (PMID 34912807, 2021). "In conclusion, Annexin A1 has been implicated in cell proliferation, apoptosis, sensitivity to chemotherapy as well as invasion and metastasis, aspects that are essential in cancer biology." (PMID 34943928, 2021). "The underlying mechanism appears to be based on the release of AnxA1 from cancer cells upon chemotherapy." (PMID 33810523, 2021). "Upregulation of ANXA1 is associated with increased resistance to chemotherapy in several cancers, but the mechanism by which it promotes resistance is unclear." (PMID 32226772, 2020).
cancer (continued). "The strength of this study is that, for the first time, we have assessed the genotypes of miR-196a in the Pakistani population and its relationship to cancer susceptibility along with its target gene ANXA1." (PMID 31777500, 2019). "A recent study suggests an association between AnxA1 cleavage and cancer aggressiveness and progression." (PMID 30884823, 2019). "Historically, Annexin A1 and A2 were first discovered in Rous sarcoma viruses major cellular substrates, which play a causative role in cancer development." (PMID 28963375, 2018). "Dysregulation of ANXA1 levels and alterations to its sub-cellular localization have been associated with the development and progression of a large number of cancers." (PMID 29614751, 2018). "Little is known about the underlying mechanisms responsible for the loss of ANXA1 expression in this type of cancer." (PMID 28754915, 2017). "It has been reported that ANXA1 from prostate-derived cancer-associated fibroblasts (CAF) is capable of inducing EMT, promoting de novo generation of CSCs and stimulating the CSC population from PCa cells." (PMID 26312765, 2015). "As previously reported, ANXA1 has been frequently implicated in cytoskeletal organization and in the acquisition of cancer cell invasion as a modulator for EMT like phenotypic switch via the transforming growth factor (TGF) signaling pathway." (PMID 26312765, 2015). "The expression of ANXA1 has been profiled in many different cancer subtypes and showed considerable success as a possible prognostic and diagnostic marker in some cancer such as hairy cell leukemia and cholangiocarcinoma." (PMID 25536365, 2014). "The results indicated that the NaB activity of growth inhibition and pro-apoptosis in DU145 cancer cells was associated with the over-expression of ANXA1." (PMID 24086397, 2013). "ANXA1 is implicated in the regulation of both apoptosis and autophagy in cancer cells." (PMID 38892394, 2024). "Likewise, ANXA1 is associated with cancer; however, its role in proliferation and metastasis is controversial." (PMID 39194522, 2024). "In addition to Fos, some other genes associatedwith cancer, such as Anxa1, Samd9, Tppp3, Slc22a3, and Ly6d, were differently regulated in both or one of the GX-rich groups,compared with the control group." (PMID 38343302, 2024). "Interestingly, in the cytoplasmic fraction, Annexin 1 (ANXA1) with known anti-inflammatory activity and loss of function or expression in cancer cells, was also downregulated." (PMID 39268460, 2024). "BC is associated with normal or elevated levels of ANXA1; however, some tumors tend to lose it, which might suggest its importance in maintaining normal breast biology as a negative regulator of cancer cell growth." (PMID 38892394, 2024). "Previous works described ANXA1 upregulated in the secretome and exosomes secreted by cancer cells, which has been associated with a major potential role of ANXA1 in promoting cancer angiogenesis, proliferation, invasion and metastatic properties of cancer cells." (PMID 36745330, 2023). "Therefore, ANXA1 modulation, as a potential pharmacological protein has been linked to the therapeutic potential of a wide range of cancers, such as breast cancer." (PMID 37507468, 2023). "ANXA1 was proven to be associated with drug resistance to promote cancer development." (PMID 37968699, 2023). "Thus, ANXA1 expression has been linked to the regulation of different cellular processes in HNC thereby affecting multiple hallmarks of cancer." (PMID 36247003, 2022). "Although ANXA1 was initially discovered due to its role in inflammation, accumulated evidence has subsequently shown that dysregulation of ANXA1 is strongly linked with tumorigenesis and the development of some cancer types." (PMID 34991599, 2022).
cancer (continued). "Thus, when cancer cells lack Anxa1 or when the host is deficient for Fpr1, the anticancer activity of anthracyclines in mice is compromised." (PMID 36429101, 2022). "Accumulating evidence denoted that aberrant expression of ANXA1 may represent potential diagnostic and treatment biomarkers in numerous human diseases, including cancer." (PMID 33531975, 2021). "Since Th2 cells are known as pro-cancer immune cells, high Th2 cell infiltration may explain the association between ANXA1 high and poor prognosis in PC patients." (PMID 33804148, 2021). "In particular, the loss of the anti-PLA2 activity of AnxA1 could represent a hallmark of cancer aggressiveness." (PMID 34208346, 2021). "ANNEXIN A1 is also implicated in various types of human cancer." (PMID 34340715, 2021). "In addition to its relationship with cancer cells, ANXA1 expression is also associated with multiple cells in the TME, such as fibroblasts, and, with angiogenesis, the generation of new vessels and metastasis." (PMID 33804148, 2021). "Consequently, overexpression of ANXA1 results in malignant proliferation of cancer cells by causing disorder in the immune system." (PMID 32226026, 2020). "Overexpression of ANXA1 is often associated with EMT in some aggressive cancers." (PMID 32226772, 2020). "ANXA1 has been previously associated with the content of EVs in various type of cancer." (PMID 30518142, 2018). "Underlying molecular mechanism of reduced ANXA1 expression in cancer has been yet undefined." (PMID 29091952, 2017). "Annexin-1 (ANXA1) plays pivotal roles in regulating various physiological processes including inflammation, proliferation and apoptosis, and deregulation of ANXA1 functions has been associated with tumorigenesis and metastasis events in several types of cancer." (PMID 29233185, 2017). "Intriguingly, ANXA1 has been both positively and negatively associated with MMPs expression in cancer, and has been shown to be the target of AGE-dependent non-enzymatic glycosylation in pulmonary endothelial cells in STZ-induced T1DM, suggestive of a link between AGE and BBB breakdown in DM." (PMID 27655189, 2016). "To determine whether the inhibition of mTOR-S6 signaling caused by annexin A1 knockdown has any functional relevance, we investigated the effects of annexin A1 knockdown on cancer cell migration." (PMID 26000884, 2015). "We also found a higher ANXA1 expression in triple negative patients, confirming previous studies; association with poor differentiation grade is also described in other types of cancers." (PMID 26137966, 2015). "Annexin 1 (ANXA1) is an endogenous anti-inflammatory protein implicated in cancer." (PMID 25536365, 2014). "It has been shown that ANXA1 over-expression in the tissues from patients with PC is correlated with poor differentiation and prognosis and seems to be associated with malignant transformation and cancer progression." (PMID 25510623, 2014). "In precancerous stages, reduced ANXA1 levels promoted monocyte differentiation toward M1 macrophages and inflammatory responses, whereas during malignant progression, upregulated ANXA1 fostered M2 macrophage polarization and cancer-associated fibroblast transformation by increasing TGF-β production." (PMID 38645221, 2024). "Current research focuses on the effects of hypermethylation and low expression of ANXA1 on cancer occurrence and progression." (PMID 40551992, 2025). "Future studies should encompass a wider range of patient samples, more diverse cancer subtypes, and longitudinal analyses in order to gain a comprehensive understanding of ANXA1 expression dynamics and its impact on immunotherapy outcomes." (PMID 40744683, 2025).
cancer (continued). "The loss of ARID1A activates Annexin A1, which aligned closely with a region targeted by EBV-associated cancers on chromosome 9." (PMID 39885374, 2025). "This represents a novel and significant mechanism by which ANXA1 inhibits tumorigenesis at the earliest stages of cancer development." (PMID 39896470, 2025). "Regarding cancer, a growing number of studies support that ANXA1 is differentially expressed in many kinds of tumors, and it is considered as a tissue-specific oncogene or oncosuppressor." (PMID 40227604, 2025). "While the prognostic value of ANXA1 has been well-documented in various cancers, its immune modulation role in CRC is still underexplored." (PMID 41283264, 2025). "ANXA1, a phospholipid-binding protein with immunomodulatory function, has been investigated in cancer." (PMID 39896470, 2025). "Taken together, our results show that the ANXA1 cytokine is responsible for the pro-apoptotic, pro-wound healing, and anti-inflammatory effects of oxidative stress-induced exosomes in cancer cells." (PMID 40520087, 2025). "Via the FPR pathway activation, neutrophil-derived ANXA1 can stimulate cancer cell invasion and metastasis, including in CRC." (PMID 41283264, 2025). "These exosomes induce apoptosis of normal cancer cells transporting ANXA1 in an Arg/N-degron pathway-dependent manner." (PMID 40520087, 2025). "Taken together, these findings support ANXA1’s central role in the angiogenesis process and, thus, targeting ANXA1 represents a promising therapeutic strategy in vascularization inhibition and, consequently, in cancer progression inhibition." (PMID 41283264, 2025). "This comprehensive analysis spanning multiple cancers further underscores the significance of ANXA1 and its family members in modulating immune responses, highlighting their potential as predictive markers for immunotherapy efficacy." (PMID 40744683, 2025). "Annexin A1 is most prominent in differentiated cells (i.e., macrophages, neutrophils) and various forms of cancers (i.e., fibrosarcoma, myeloma, breast, pancreatic)." (PMID 39982229, 2025). "ANXA1 involvement in cancer progression and metastasis is achieved by EMT initiation via multiple signaling cascades, e.g., PI3K/AKT, Wnt, TGF-β, MAPK/ERK, Notch, JNK, and p38 MAPK." (PMID 41283264, 2025). "By using proteomics analyses, we also demonstrate that exosomes secreted from cancer cells upon oxidative stress are enriched apoptotic proteins including pro-apoptotic and anti-inflammatory cytokine ANXA1." (PMID 40520087, 2025). "This mechanistic insight provides a new perspective on how ANXA1 facilitates an immunosuppressive environment, promoting cancer progression and resistance to immunotherapies." (PMID 40744683, 2025). "Future studies will focus on exploring the effect of MDX-124 on other cancer-related processes shown previously to be driven by ANXA1 overexpression including invasion and migration, drug resistance and angiogenesis." (PMID 38200229, 2024). "Previously, higher externalization of PS in larger EV subtypes positive for annexin A1 compared to smaller EV subtypes was also shown, especially for cancer cells." (PMID 38179654, 2024). "ANNEXIN signaling elicits proinvasive and protumoral properties in a number of cancers, whereby neutrophil microvesicles enriched in Annexin A1 and TGFβ are immunosuppressive." (PMID 38358352, 2024). "Here we show that MDX-124 significantly reduced proliferation (p < 0.013) in a dose-dependent manner across a panel of human cancer cell lines expressing ANXA1." (PMID 38200229, 2024). "Although specific clinical trials targeting ANXA1 are limited, its involvement in cancer progression highlights its potential as a therapeutic target." (PMID 38892394, 2024). "It would mean expressing ANXA1 and is beneficial for cancer cells, which makes it a potential target for anti-cancer therapy and the explanation of emerging drug resistance of cancer cells after treatment." (PMID 38892394, 2024).